Y_RNA (Y RNA )
Gene: Miscellaneous RNA gene on chromosome 2 (28,972,414 to 28,972,521, reverse strand). Ensembl gene ENSG00000200283.
Homologues: Orthologues: chimpanzee Y_RNA (97% identical). Paralogues in human: Y_RNA (79% identical), Y_RNA (78% identical), RNY1 (77% identical), Y_RNA (77% identical), Y_RNA (76% identical), RNY1P14 (75% identical), RNY1P7 (75% identical), Y_RNA (75% identical), RNY1P11 (74% identical), RNY1P5 (74% identical), Y_RNA (74% identical), RNY1P3 (73% identical), and 89 more.